CD80 (CD80 molecule)
Diseases named in the same sentence as CD80 in open-access papers (continued):
Sharing a sentence is not in itself a finding about the gene and the disease.
infection (continued). "Expression levels of the DC maturation markers CD80 and MHC class II were assessed on DC which were isolated from spleens and lymph nodes of LCMV-infected fgl2+/+ or fgl2−/−mice on day 1 post LCMV WE infection." (PMID 24146739, 2013). "After infection, cells were analyzed for the expression of costimulatory molecules (CD86, CD80, and PD-L1), cytokine production, and the ability to stimulate allogenic CD4+ T cell proliferation." (PMID 23829893, 2013). "Expression levels of CD86, CD80 and CD40 on mDCs were comparable between C3−/− and WT mice during the course of infection." (PMID 23326231, 2013). "In summary, BDCA1+ mDCs isolated freshly from blood respond faster and more pronounced compared to in vitro differentiated moDC with regard to CD80 and PDL1 induction upon EV1 infection." (PMID 23638101, 2013). "EV7 which replicates rapidly in moDC and, similar to EV7 infection of BDCA1+ mDCs, induces massive cell death, greatly reduced CD80 expression in both DC subsets." (PMID 23638101, 2013). "Surface expression of MHC II, CD40, CD80, and CD86 were significantly (p<0.05) up-regulated at 20 h after infection with O. tsutsugamushi, even though the levels of expression were lower than those of cells stimulated with LPS." (PMID 23301113, 2013). "Subsequent LVS infection, Acai PS enhanced surface expression of CD11b, CD40, CD80, CD86, TLR2, and MHC class II in a dose-dependent fashion, while TLR4 expression was downregulated in both mock- and LVS- infected macrophages." (PMID 22438809, 2012). "CD80 and CD86 expression is muted during chronic infection, similar to what has been observed at early times (∼5 hr) post infection." (PMID 22911108, 2012). "IDO is upmodulated during antigen presentation by the engagement of CTLA-4/B7.1/B7.2 (CD80/CD86) molecules on lymphocytes and human dendritic cells (DCs), in response to infection and tissue inflammation (TNF-α, PGE2, IFN-α/β/γ secretion)." (PMID 23213488, 2012). "A recent study showed, albeit for BCG, that MHC-II, CD80, CD86, and CD40 are down-tuned during chronic phase of infection." (PMID 22719245, 2012). "Microglia also display differences in CD80 and CD86 expression following TMEV infection in vivo, which differs from the expression patterns observed with our in vitro studies in that upregulation is delayed." (PMID 21494618, 2011). "In vivo, however, the infection induced the expression of the co-stimulatory molecules CD86 and CD80 as well as MHC class II by CD11c+ cells in wild type and TLR2/4 double-deficient mice with comparable efficiency." (PMID 22096480, 2011). "Following infection with HTLV-1, CD80 and CD86 are constitutively expressed suggesting that HTLV-1-infected CD80+/CD86+ T cells serve as antigen presenting cells, leading to a sustained proliferation of T cells." (PMID 21994790, 2011). "Microglia display differential expression patterns of antigen presentation molecules, I-As, H-2Ks, CD80, CD86, but express elevated and sustained levels of B7-H1 as early as day 3 post-infection compared to sham-infected microglia." (PMID 21494618, 2011). "MHCII and costimulatory molecules CD40, CD80, and CD86 had an average 0.5 fold decrease in their MFI intensity from three to ten weeks after infection." (PMID 20625513, 2010). "Expression of the costimulatory molecules CD80 and CD86 was markedly increased in all animals at 2 weeks post infection indicative of rapid mDC activation." (PMID 21203477, 2010). "We compared BMDM obtained from fresh and frozen BM cells and found that both are similarly able to trigger the expression of CD80 and CD86 in response to LPS or infection with the intracellular bacteria Legionella pneumophila." (PMID 21179419, 2010). "CD80 and CD86 single-knockout mice are able to control MHV-68 infection, while CD80/CD86 double-knockout mice fail to maintain efficient long-term control of MHV-68, demonstrating that these molecules play overlapping roles in the control of MHV-68." (PMID 19621080, 2009).
infection (continued). "At 0, 12 and 18 h following infection, cells were harvested and stained with mAbs specific for CD40, CD86, CD80, and MHC class II I-Ad." (PMID 18412969, 2008). "DCs isolated from spleens of mice 4 days after infection showed a moderately activated phenotype, as demonstrated by increased expression of CD40 and CD80, confirming previous reports." (PMID 16611373, 2006). "DCs isolated from infected animals 12 and 20 days after infection, however, showed a reduced level of activation, with lower levels of CD40, CD80, CD86 and MHC class II molecules on their surface compared with DCs from uninfected animals." (PMID 16611373, 2006). "Furthermore, primary monocytes expressed CD80, CD86, and HLA-DR upon direct infection or through potential paracrine stimulation." (PMID 41280933, 2025). "Compared to the phosphate-buffered saline (PBS) and Adv-Ctrl groups, infection with Adv-NF and Adv-NGS at a MOI of 2 both resulted in a 2-fold expansion of CD80+CD86+ mouse DCs, demonstrating a potency comparable to that of lipopolysaccharide (LPS) stimulation." (PMID 40195559, 2025). "This abortive infection induces the activation of monocytes, which subsequently produce various proinflammatory cytokines and chemokines and express MHC class II and the costimulatory molecules CD80 and CD86, which are important for T-cell activation." (PMID 41280933, 2025). "Altogether, our study suggests that reduced latency correlated with reduced levels of inflammatory molecules and blocking or reducing expression of CD80 could be used to mitigate the immune responses, therefore controlling HSV-induced infection." (PMID 39339855, 2024). "Compared with the PEDV-CV777 strains infection group and the negative group, the percentage of CD80, MHC II, and IgM expressed on the surface of B cells from neonatal piglets was significantly decreased after thePEDV-QY2016 strains infection at 24 hpi." (PMID 38585694, 2024). "We used a customized gene expression panel (see Section 2) to evaluate the effects of the absence of CD80 expression or overexpression of CD80 during HSV-1 primary infection." (PMID 39339855, 2024). "Compared to patients who did not have any post-operative infection, patients who developed an infection had an increase in monocyte count (p = 0.0037) and CD4+ lymphocyte IL-7R (p < 0.0001) and a decrease in monocyte CD80 (p = 0.0279) and CXCR4 expression (p = 0.0220)." (PMID 38655251, 2024). "Monocyte chemokine receptors (pre- and post-operative monocyte CXCR4) and receptors involved in antigen presentation (CD80) were the greatest discriminators between patients with and without post-operative infections (loading vector coefficient of > 0.8)." (PMID 38655251, 2024). "While it is expressed on antigen-presenting cells, we customized a gene expression panel to evaluate the absence of CD80 during HSV-1 primary infection." (PMID 38376148, 2024). "When quantifying the cell membrane markers, we found that after 1.5 h of infection, macrophages infected with vegetative P. aeruginosa cells expressed high levels of CD80/CD86, but not CD206." (PMID 36920189, 2023). "Since CD80 and CD86 are required for further T cell activation, increased expression would also likely result in enhanced T cell activation and more rapid clearance of infection in vivo." (PMID 37213504, 2023). "We then investigated whether such trogocytosis of CD80 and CD86 by CD8+ T cells was merely an in vitro phenomenon or whether it also occurred upon infection in vivo." (PMID 36309492, 2022). "Transcripts indicating antigen presentation (Cd11c, Cd80, and Cd86) are enriched in non-infected cells at later stages of infection." (PMID 35663950, 2022). "The expression of MHC II, CD86, and CD80 was not differentiable between infection routes for mDCs and CD8+ DCs, whereas there was a higher expression on pDCs in i.p. infected mice." (PMID 35898505, 2022).
infection (continued). "However, infection of BMDCs with LDPm led to a gradual decrease in LPS-stimulated CD40, CD80, and CD86 expression, with peak inhibition observed at 24 h postinfection." (PMID 35924848, 2022). "In addition, these cells displayed elevated expression of CD80 and CD86 in the blood and spleen after 30 days of infection, which remained high in the spleen, and particularly in the MLN, after 60 days." (PMID 34685494, 2021). "BC-3 cells appeared to have a distinct phenotype with no expression of CD80 and CD86, which is likely caused by their inherent infection with Kaposi's sarcoma-associated herpesvirus." (PMID 33666760, 2021). "Notably, the majority chemokine ligand, which induced cells of the immune system to enter the site of infection, CCL-2, CD80 and CD68 of TAMs, IRF5 and NOS2 of M1, CD163 and MS4A4A of M2 were strongly related to JAK1 expression in LUAD (all P value < 0.0001)." (PMID 34587898, 2021). "In addition, HIF-1α KO mice infected with B. abortus exhibited reduced frequency of splenic CD80+ and NOS2+ inflammatory macrophages in comparison with HIF-1α WT during the early phase of the infection." (PMID 33989349, 2021). "This population was already described in other infection settings and is characterized by the exclusive expression of PD-L1 (defining marker for P1-pDC) and absence of CD80." (PMID 33857267, 2021). "Surprisingly, the expression of some M2 surface markers decreased only slightly and the CD80 M1 surface marker did not increase upon either infection or IFN-γ/LPS stimulation." (PMID 34399615, 2021). "As it occurred in transfection assays with the m138 mutant plasmids defective in these Ig domains, infections with MCMVm138ΔIg2 or MCMVm138ΔIg2/Ig3 led to decreased cell-surface density of CD80 but not ICOSL." (PMID 33459589, 2021). "Before infection, FSClow DCs of uninfected chickens showed a higher expression of MHC-II and more cells that were positive for the costimulatory molecules CD40 and CD80 compared to FSChigh DCs." (PMID 34404469, 2021). "Consequently, during infection or inflammation, APCs upregulate CD86 and CD80 and both signals, TCR and CD28, are activated, so that T-cells perform target killing, with long-term persistence." (PMID 34771581, 2021). "NK cell depletion led to a substantial increase of both MCMVΔm138 and MCMVm138ΔIg2 infection in this organ, but importantly, MCMVm138ΔIg2, which was downmodulating CD80 but not ICOSL, was still heavily attenuated as compared to MCMVwt under these conditions." (PMID 33459589, 2021). "While CD80+ T lymphocytes are essential for protection after intraperitoneal infection, both CD4+ and CD8+ T lymphocyte subpopulations play a substantive protective role in the case of a peroral, i.e. natural route of infection." (PMID 32539803, 2020). "This may be because EBV activates B lymphocytes upon infection, leading to increases in the abundances of their activator antigens CD5, CD80, and CD86, which play major roles in maintaining immune stability." (PMID 32149157, 2020). "According to recent studies, crosstalk occurs between NK cells and macrophages, which plays an important role in anti-infection responses, and macrophages are activated by IFN-γ, which is mainly produced by NK cells and CD4+ T cells via increasing receptors such as CD80, CD86 and MHC II." (PMID 33327533, 2020). "The T cell co-stimulatory molecule CD80 was found to be downregulated in DCs in a manner dependent on ICP22 binding to the CD80 promoter, which seems to limit the pathogenesis of the virus as well as delaying the immune response to infection." (PMID 33374862, 2020). "Upon initial infection, we found a small but non-significant increase in CD80 with live MAP or KMAP, which increased significantly at 24 h and 48 h." (PMID 32635236, 2020).
infection (continued). "It was observed that PCV2 infection in vivo impaired DC functions: at the peak of virus proliferation (7 days post-infection), moDC generated from infected pigs presented reduced MHC II and CD80/86 expressions, lower levels of IL-10, IL-12, IL-8, MIP-1β, and reduced ability to stimulate T cells." (PMID 31100880, 2019). "Infection with the S. aureus USA300 WT or the S. aureus Δαβδ mutant strain induced the up-regulation of MHCII, CD86, CCR7, CD80, CD40, and PD-L2 on all DC subsets in the spleen starting 6 h pi compared to PBS-treated mice as analyzed by flow cytometry staining." (PMID 31134074, 2019). "Deficiency or knockdown of GDF15 in DCs increased the expression of MHCII, CD40,CD80 CD83, and CD86, while over expression of GDF15 either by using GDF15 TG DCs or infection with GDF15-Ad reduced the expression of these molecules, in comparison with WT untreated DCs." (PMID 30425709, 2018). "The percentage of CD80+ monocyte and granulocyte populations did not change as a result of either infection or treatment." (PMID 30072754, 2018). "Like LASV, MOPV infection also fails to activate DCs in culture as evidenced by the failure to upregulate CD80, CD86, CD54, CD40, and HLA-abc." (PMID 28498311, 2017). "To phenotypically characterise pDC during early P. falciparum infection we assessed maturation markers; CD86, CD40, CD80, HLA-A,B,C, HLA-DR and CD123 (IL-3Rα) expression on pDC before and at peak-infection for participants infected with either 150 pRBC or 1,800 pRBC." (PMID 28572564, 2017). "Infection with live Gram-negative bacteria had led to an elevated inflammatory response in miR-146a−/− BMMs, manifested by elevated CD80 and MHC-II cell surface expression compared to WT, miR-155−/− and DKO BMMs, which displayed similar response." (PMID 29021573, 2017). "AAL and AAS treatment induced maximum up-regulation of CD80 (11.7% and 15.7%) and CD86 (12.6% and 15.4%) expression along with CD80/86 (13.1% and 17.0%) co-expression in comparison with infection control where as in AMB and ART treated groups, the effect was less pronounced." (PMID 25568967, 2015). "In naïve mice, CD80 was not widely expressed by RORγt+ ILCs, but after infection this costimulatory molecule was expressed by a subset of group 3 ILCs." (PMID 26010337, 2015). "Infection with Col cl1.7, but not with Y strain, led to an increase in the expression of CD80 and CD86." (PMID 26147698, 2015). "Following infection with either PRRSV-1 or PRRSV-2 strains after 24 h, PRRSV-nucleoprotein (N-protein)+ and N-protein− moDCs derived from the same microculture were analyzed for expression of swine leukocyte antigen-DR (SLA-DR) and CD80/86." (PMID 25990845, 2015). "We investigated whether the expression of CD80 and CD86, monocyte ligands for co-stimulatory molecules, was modified after 72 hours of infection with Y strain or Col cl1.7." (PMID 26147698, 2015). "Surprisingly, while infection with Y strain and Col cl1.7 both led to an increase in the intensity of expression of HLA-DR and TLR-2, the two isolates affected differently the expression of CD80 and CD86." (PMID 26147698, 2015). "Thus, we examined the expression of MHC class II and co-stimulatory molecules CD80 and CD86 on PECs from immunized mice post-infection." (PMID 26114641, 2015). "Consistent with this, blocking CD80/86 at d11 and 13 post infection did not affect the proportion of Th1 cells in the medLN or lung 15 days post infection." (PMID 25347065, 2014). "Indeed, the activation of colonic CD45+MHCIIhiCD11c+F4/80−CD11b+ DCs, co-stimulatory molecules, CD80/CD86, and co-inhibitory, B7-H1, were unchanged or significantly depressed during infection, suggesting inhibition of immune functions." (PMID 24945934, 2014). "Although CD80 and CD86 were expressed on each of the cell populations, there was little increase in the expression of CD80 or CD86 in any of the cell populations in response to infection." (PMID 23390557, 2013).
infection (continued). "Following infection with 2×106 PFU LCMV WE, we observed enhanced activity of DC in fgl2−/− mice as early as day 1 pi as shown by increased expression of the maturation markers CD80 and MHC-II on the isolated cells and increased plasma IFNα levels." (PMID 24146739, 2013). "Upon pathogen infection, DCs capture foreign antigen and undergo maturational changes including increased surface expression of major histocompatibility complex (MHC) and costimulatory molecules, such as CD40, CD80, and CD86." (PMID 23301113, 2013). "The expression levels of CD80 and MHC class II on DC from fgl2−/− mice were significantly higher compared to fgl2+/+ mice indicating that targeted deletion of fgl2 leads to increased activation of DC following infection with LCMV WE." (PMID 24146739, 2013). "In contrast, upon EV1 infection there was no further increase of CD80, CD86 or PDL1 expression compared to non poly I:C-stimulated, EV1-infected cells." (PMID 23638101, 2013). "MVA-C infection of human monocyte derived dendritic cells (moDCs) induced the expression of HIV-1 antigens at high levels from 2 to 8 hpi and triggered moDCs maturation as revealed by enhanced expression of HLA-DR, CD86, CD40, HLA-A2, and CD80 molecules." (PMID 22536391, 2012). "In further analysis of airway CD11c+ Class IIhi cells, there was an increased proportion of cells expressing CD80/86, as well as increased recovery of both CD11b+ CD103− and CD11b− CD103+ dendritic cell populations 24 hr after secondary infection compared to primary." (PMID 21647373, 2011). "Infection with this pathogen resulted in up regulation of MHC I and MHC II, CD40, CD54, CD58, and CD80, a phenotype consistent with the activation of the DC, suggesting that infected DC produce cytokines that lead to maturation, and possibly to migration and antigen processing and presentation." (PMID 21777464, 2011). "Through the analysis of correlation, both CD80+ pDCs (r = 0.462, P = 0.003) and CD86+ pDCs (r = 0.359, P = 0.023) were found to show a positive correlation with the time of infection, which seems to imply that more and more pDCs are activated following disease progression." (PMID 22174949, 2011). "The absence of CD28, CD40, CD40L, CD80/CD86 or 4-1BBL did either not affect viral replication in the early phase of infection or early viral titers were rather increased." (PMID 19621080, 2009). "CD40 and CD86 were increasingly expressed during the course of infection (data not shown); in contrast, CD80 failed to be upregulated." (PMID 19436710, 2009). "Our observation of increased intermediate monocytes (with presumably higher MHC-II, CD80, and CD86 expression) in the FABP-immunized group suggests ongoing antigen immune activation, consistent with prior reports that intermediate monocytes upregulate these markers during infection or immunization." (PMID 41376640, 2025). "Interestingly, pDC showed increased MFI for CD40, CD80, CD86, and MHC-II on the molecules positive pDC, respectively, after BCG immunization, especially at 4 h and 12 h post-infection, suggesting high expression levels of these molecules on the limited positive pDC." (PMID 36977141, 2023). "Similar to WT STm infection, genes involved in the regulation of immune responses (ATF3, BATF3, ETS2, IRF9, NFκB2, MAFA, TNFAIP3), effector functions, (CCL4, CD200L, CD40, CD72, CD80, IL18) and TLR signaling, (EAF2, TLR15, TRAF3IP2, TOLLIP) were upregulated after ΔprgH STm infection in both models." (PMID 37854334, 2023). "Interestingly, determination of the level of expression of macrophage antigen presentation/processing and activation markers (MHCII, CD80, CD86 and CD40) by flow cytometry after 48 h of infection revealed that all markers were significantly increased in cells infected with the sucT mutant." (PMID 37669276, 2023). "However, the changes in the expression of CD80 were not significant, either before and after infection or between WT-infected and KO mice (P > 0.05)." (PMID 34692568, 2021).